EIF3K (eukaryotic translation initiation factor 3 subunit K)
Description:
Component of the eukaryotic translation initiation factor 3 (eIF-3) complex, which is required for several steps in the initiation of protein synthesis. The eIF-3 complex associates with the 40S ribosome and facilitates the recruitment of eIF-1, eIF-1A, eIF-2:GTP:methionyl-tRNAi and eIF-5 to form the 43S pre-initiation complex (43S PIC). The eIF-3 complex stimulates mRNA recruitment to the 43S PIC and scanning of the mRNA for AUG recognition. The eIF-3 complex is also required for disassembly and recycling of post-termination ribosomal complexes and subsequently prevents premature joining of the 40S and 60S ribosomal subunits prior to initiation. The eIF-3 complex specifically targets and initiates translation of a subset of mRNAs involved in cell proliferation, including cell cycling, differentiation and apoptosis, and uses different modes of RNA stem-loop binding to exert either translational activation or repression.
Synonyms: EIF3S12; ARG134; HSPC029; MSTP001; PTD001; PRO1474; PLAC-24; M9; EIF3-p28; PLAC24
Tractability: Small molecule: a structure with a bound ligand is known. PROTAC: ubiquitination databases record sites on it; its protein half-life has been measured.
Gene: Protein-coding gene on chromosome 19 (38,619,055 to 38,636,959, forward strand). Ensembl gene ENSG00000178982.
Subcellular location: Nucleus; Cytoplasm
Subcellular location (Human Protein Atlas): Cytosol
Pathways (Reactome):
Metabolism of proteins: Formation of a pool of free 40S subunits; Formation of the ternary complex, and subsequently, the 43S complex; GTP hydrolysis and joining of the 60S ribosomal subunit; L13a-mediated translational silencing of Ceruloplasmin expression; Ribosomal scanning and start codon recognition; Translation initiation complex formation
Gene Ontology:
Molecular function: protein binding; translation initiation factor activity; ribosome binding; RNA binding
Biological process: translational initiation; formation of cytoplasmic translation initiation complex; cytoplasmic translational initiation; regulation of translational initiation
Cellular component: cytosol; eukaryotic translation initiation factor 3 complex; membrane; cytoplasm; eukaryotic 43S preinitiation complex; eukaryotic 48S preinitiation complex; nucleus
Genetic constraint (gnomAD): Loss-of-function variants: 27 observed, 35.77 expected, observed/expected ratio (o/e) 0.75, 90% interval 0.56 to 1.04. The upper end of that interval is the gene's LOEUF score, 1.04, which puts it in group 4 of 6, group 1 being the genes least tolerant of losing a copy. Missense variants: 232 observed, 289.1 expected, observed/expected ratio (o/e) 0.8, 90% interval 0.72 to 0.89. Synonymous variants: 105 observed, 111.38 expected, observed/expected ratio (o/e) 0.94, 90% interval 0.8 to 1.11.
Homologues: Orthologues: chimpanzee EIF3K (100% identical), guinea pig EIF3K (99% identical), mouse Eif3k (99% identical), macaque EIF3K (97% identical), dog EIF3K (96% identical), rat Eif3k (96% identical), rabbit EIF3K (95% identical), tropical clawed frog eif3k (91% identical), zebrafish eif3k (84% identical), Drosophila melanogaster eIF3k (48% identical), Caenorhabditis elegans eif-3.K (39% identical).
Diseases named in the same sentence as EIF3K in open-access papers:
EIF3K is named in the same sentence as 30 diseases in open-access papers, as found by Europe PMC text mining. Sharing a sentence is not in itself a finding about the gene and the disease. The quoted sentences say what the papers report.
breast cancer (5 papers, 2013 to 2025). A primary or metastatic malignant neoplasm involving the breast. "And a higher transcriptional level of EIF3J and EIF3K was associated with advanced pathologic grades and poor outcomes for breast cancer patients." (PMID 35040374, 2022).
glioma (3 papers, 2019 to 2023). A benign or malignant brain and spinal cord tumor that arises from glial cells (astrocytes, oligodendrocytes, ependymal cells). "Our profiling results were in accordance with above studies that increased expression of EIF3K was associated with decreased survival of glioma patients and increased glioma grades." (PMID 32565801, 2020). "Based on the peer investigations of pathogenesis on both schizophrenia and glioma, we have the reason to advise EIF3K as the potential targets of the mechanism study of schizophrenia and glioma, resulting new therapies for both diseases." (PMID 32565801, 2020). "Recently, systematically profiling found that the expression of eIF3b, eIF3i, eIF3k, and eIF3m was increased with the glioma grade and poorer overall survival." (PMID 32565801, 2020). "The results indicated that the expression levels of eIF3a, eIF3b, eIF3i, eIF3k, eIF3l and eIF3m were significantly (P < 0.05) correlated to the OS of glioma patients in both datasets." (PMID 31171919, 2019). "We also compared the prognosis ability of eIF3i, eIF3k alone or in combination, and the results showed that the expression of eIF3i was the more robust in stratifying the survival of glioma in various pathological subgroups." (PMID 31171919, 2019). "We noticed that the elevated expression of eIF3i (located on chromosome 1p) and eIF3k (located on chromosome 19q) were significantly correlated with the increased malignancy of glioma." (PMID 31171919, 2019). "Based on this, we further investigated the prognostic value of eIF3i (located on chromosome 1p), eIF3k (located on chromosome 19q), and the combination of eIF3i and eIF3k in gliomas with specific molecular features." (PMID 31171919, 2019). "Among eIF3i, eIF3k alone or in combination, the expression of eIF3i was the more robust in stratifying the survival of glioma in various pathological subgroups." (PMID 31171919, 2019). "Considering the clinical implication of 1p/19q codeletion in gliomas, we also compared the prognosis ability of eIF3i, eIF3k alone or in combination in stratified gliomas from CGGA dataset." (PMID 31171919, 2019). "Importantly, we noticed that the expression of both eIF3i (located on chromosome 1p) and eIF3k (Located on chromosome 19q) were positively correlated with the malignancy of gliomas." (PMID 31171919, 2019). "Based on these, we systemically investigated the prognostic values of eIF3i (located on chromosome 1p) and eIF3k (located on chromosome 19q) in stratified glioma and identified that the expression of eIF3i was closely correlated with the OS of patients in serval stratified glioma subgroups." (PMID 31171919, 2019). "CAMK2D, EIF3K, MPC2, MYL12B, PAM, and SLC35B4, selected from the schizophrenia dataset and TCGA, were reevaluated in CGGA through gene expression in glioma grading and survival curves between patients having high level of gene expression and those having low level of gene expression." (PMID 32565801, 2020). "The results showed that the expression of eIF3i had the superior predictive efficiency compared with eIF3k expression, combined expression of eIF3i and eIF3k, WHO grade and subgroups of WHO 2016 for predicting survival of patients with 1p/19q non-codeletion glioma in the CGGA dataset." (PMID 31171919, 2019).
cervical cancer (2 papers, 2020 to 2025). A primary or metastatic malignant neoplasm involving the cervix. "Four of these genes were also significantly up-regulated in cervical cancer cell lines (SiHa and C33A):EIF3K (p = 0.0092), RACK1 (p = 0.0086), TAPBPL (p = 0.0011) and BTNL8 (p = 0.0012)." (PMID 32025240, 2020).
colitis (2 papers, 2018 to 2021). Inflammation of the colon. "This suggests decreased Eif3k mRNA expression in monocytes/macrophages in our data is part of a compensation mechanism for increased ER stress in these populations during colitis." (PMID 30542349, 2018).
COVID-19 (2 papers, 2022 to 2023). A disease caused by infection with severe acute respiratory syndrome coronavirus 2. "When analyzing the DEGs using the bioinformatic platform Enrichr-KG, the most relevant transcription factors potentially driving the differences in kidney gene expression between COVID-19 AKI and non-COVID-19 AKI were POLR2L, EIF3K, BOLA3, RFXANK, and ZNF576." (PMID 38003268, 2023).
co-infection (1 paper, 2012). "HCV and HIV co-infection down-regulated tropomyosin alpha-4 isoform 1, pyruvate kinase isozyme M1/M2, an ER ATPase, GST, EIF3K, and GTPase Ran of which the first three were down-regulated in HIV-1 but not in HCV-infected samples." (PMID 22958358, 2012).
leukemia (1 paper, 2022). A malignant (clonal) hematologic disorder, involving hematopoietic stem cells and characterized by the presence of primitive or atypical myeloid or lymphoid cells in the bone marrow and the blood. "There were many leukemia-related genes in the up-regulated genes of K1 group, such as UBB (P=1.56e-50), MIF (P=2.76e-50), DRAP1 (P=1.72e-49), RPS25 (P=1.9e-49), EIF3K (P=4.77e-49), SSNA1 (P=1.27e-48), GPX4 (P=3.01e-48), PHB2 (P=7.13e-48), NME2 (P=2.44e-47) or CFL1 (P=4.07e-47)." (PMID 36408189, 2022).
oligodendroglioma (1 paper, 2019). A well-differentiated (WHO grade II), diffusely infiltrating neuroglial tumor, typically located in the cerebral hemispheres. "Both eIF3i and eIF3k had the highest expression in IDH-wildtype GBM, but had the lowest expression in IDH-mutant, 1p/19q codeletion, oligodendrogliomas." (PMID 31171919, 2019).
oral cancer (1 paper, 2023). "However, when APP/PS1 combination was compared with APP/PS1 + PE, we identified 772 DEGs, which were found to be enriched in EIF3K and REST transcription factors, both shown to regulate the mTOR signaling pathway in adipocyte yeast and oral cancer cells, respectively." (PMID 39081972, 2023).
testicular tumor (1 paper, 2025). "In addition to SPTBN4, 31 other molecules were analyzed, revealing potential testicular tumor markers such as TPI1, HMGN1, UGCG, NCL, SET, and EIF3K." (PMID 40321316, 2025).
virus infection (1 paper, 2024). "Unlike other translation initiation factors involved in virus infection, the anti-CHIKV activity of eIF3k is mediated by its HAM protein domain in a translation-independent manner." (PMID 39261662, 2024).
infection (9 papers, 2011 to 2024). The state of being infected such as from the introduction of a foreign agent such as serum, vaccine, antigenic substance or organism. "Our results confirmed the strong nuclear localization of eIF3k (D mock infection) and revealed the translocation of eIF3k from nucleus to cytosol induced by CHIKV infection." (PMID 39261662, 2024). "This suggests that SPCS3 and eIF3k may work together to inhibit CHIKV upon infection." (PMID 39261662, 2024). "We compared different arthritogenic alphavirus infections in eIF3k KO 293T cells, including SINV that shows similarly low infection levels in primary monocyte-derived macrophages as ONNV." (PMID 39261662, 2024).
tumor (9 papers, 1994 to 2025). "The expression of eIF3b, eIF3i, eIF3k and eIF3m was increased with the tumor grade, and was associated with poorer overall survival [All Hazard ratio (HR) > 1 and P < 0.05]." (PMID 31171919, 2019). "Highly mutated genes like BARD1, MALT1, BRCA1/BRCA2, EIF3K, PTEN, FGFR2, and MAP3K1 were also found to overlap with SVs of the tumor sample that were identified by one or more technologies in our study." (PMID 36514120, 2022). "In silico, increased gene expression over all four tumor grades was determined for eIF3B, eIF3I, eIF3K and eIF3M." (PMID 33807050, 2021).
cancer (5 papers, 2016 to 2024). A tumor composed of atypical neoplastic, often pleomorphic cells that invade other tissues. "Exosomal circ-EIF3K from cancer-associated fibroblast via modulating the miR-214/PD-L1 axis could enhance CRC progression." (PMID 36405753, 2022). "In the NDRG1 module, PSMD2 is overexpressed in many cancer cells, whereas PABPC1, EIF4G1, EIF3H, EIF3E, and EIF3K are RNA translational control members." (PMID 26735889, 2016). "Aberrant expression of various eIF3 subunits were detected in various human cancers but not for eIF3K." (PMID 35008858, 2021).
EIF3K also shares sentences with these, for which no sentence is quoted: polycystic kidney disease (2 papers); Acute hepatitis (1); astrocytoma (1); B-cell lymphoma (1); breast tumor (1); epilepsy (1); genetic dementia (1); hereditary spastic paraplegia (1); inflammatory bowel disease (1); liver diseases (1); ovarian carcinoma (1); ovarian tumour (1); pertussis (1); pneumonic (1); prostate carcinoma (1); schizophrenia (1).